LINC00499 (long independently transcribed non-coding RNA 499)
Synonyms: LINC00500
Gene: Long non-coding RNA gene on chromosome 4 (138,309,613 to 138,663,403, forward strand). Ensembl gene ENSG00000251372.
Gene Ontology:
Biological process: SRP-dependent cotranslational protein targeting to membrane, signal sequence recognition
Cellular component: signal recognition particle, endoplasmic reticulum targeting